YTHDF2 (YTH N6-methyladenosine RNA binding protein F2)
Diseases named in the same sentence as YTHDF2 in open-access papers (continued):
Sharing a sentence is not in itself a finding about the gene and the disease.
leukemia (continued). "In leukemia, particularly AML, LSCs exhibit a much stronger dependency on YTHDF2 compared to normal HSCs." (PMID 41403953, 2025). "For instance, YTHDF2 accelerates decay of GLUT4 mRNA in BRCA,253 while facilitates expression of PFKP and LDHB in leukemia, leading to opposite effects." (PMID 38531882, 2024). "The response was associated with immune cell abundance and induced the proteomic profiles of leukemia cells to disrupt survival pathways and significantly reduced MCL1 and YTHDF2 to potentiate leukemic cell death." (PMID 37386016, 2023). "YTHDF2, overexpressed in human AML samples, is considered to facilitate leukemia initiation and LSC maintenance by shortening the half-life of various m6A transcripts in favor of LSC functions and regulating mRNA decay in an m6A-dependent way." (PMID 35720276, 2022). "Scholars have reported that R-2-hydroxyglutarate (R-2HG) abates FTO/m6A/YTHDF2-mediated upregulation of phosphofructokinase platelet (PFKP) and lactate dehydrogenase B (LDHB) which suppress aerobic glycolysis and exert an anti-tumor effect in R-2HG-sensitive leukemia cells." (PMID 36035161, 2022).
viral infection (22 papers, 2016 to 2025). "During viral infection, the enzymatic activity of ALKBH5 is reduced in host cells, which leads to the downregulation of the α-ketoglutarate dehydrogenase (OGDH)-itaconate pathway associated with viral infection mediated by YTHDF2." (PMID 38957616, 2024). "Increased YTHDF2 expression was observed in response to viral infection and was associated with the activation of the transcription-factor signal transducer activation of transcription 5 (STAT-5), which activates host antiviral pathways mediated by IFN-γ." (PMID 36144356, 2022). "The viral infection successfully restored YTHDF2 expression across major hippocampal subregions, including CA1–CA3 and DG." (PMID 40959883, 2025). "NK cells exhibit higher levels of YTHDF2 compared to other immune cells, and YTHDF2 expression is significantly upregulated in NK cells upon activation by tumors, viral infections, and cytokines, such as IL-15." (PMID 39686999, 2024). "Deletion of YTHDF2 leads to increased up‐regulation of interferon‐stimulated genes in response to viral infection or inactivated viral agents, inhibiting the replication of various viruses in an interferon signal‐dependent manner." (PMID 39135292, 2024). "Particularly, YTHDF2, a reader protein that promotes m6A RNA degradation, is considered an antiviral factor in the setting of viral infection." (PMID 39597541, 2024). "During viral infections, YTHDF2 regulates perforin production, enhancing NK cell‐mediated antiviral activity." (PMID 39135292, 2024). "Mechanically, FMDV VP1 promotes autophagy during virus infection and interacts with and degrades YTHDF2 (YTH N6-methyladenosine RNA binding protein F2) in an AKT-MTOR-dependent autophagy pathway, resulting in an increase in GTPBP4 mRNA and protein levels." (PMID 38516932, 2024). "In other words, YTHDF2 cleavage during viral infection plays a pivotal role in benefiting viral replication." (PMID 39597541, 2024). "Our results showed the upregulation of the DUSP1 transcript during bacterial and viral infections, which was reversed by m6A- and YTHDF2-mediated transcript degradation." (PMID 36625590, 2023). "Deletion of METTL3 or YTHDF2 reader led to an increase in the induction of interferon-stimulated genes following a viral infection or after stimulation with an inactivated virus." (PMID 36085064, 2022). "Recent discoveries on YTHDF2 highlighted that YTHDF2 has a critical effect on regulating neural development, hematopoietic stem cell proliferation, cancer development, viral infection, and other physiological and pathological processes." (PMID 36277978, 2022). "The partial knockdown of YTHDF1 or YTHDF3 in Jurkat cells increased HIV-1 infection by three- to four-fold (p<0.005), while YTHDF2 knockdown slightly increased viral infection at 24 hpi." (PMID 27371828, 2016). "Although no literature has directly reported the involvement of lactylation in regulating YTHDF2 expression during viral infection, research has demonstrated that YTHDF2 binding to m6A sites on HIV-1 transcripts significantly enhances the stability of viral RNAs." (PMID 40720394, 2025). "In fact, DUSP1 is under the tight control of m6A and YTHDF2 during bacterial and viral infections." (PMID 36625590, 2023). "Similarly, the deletion of METTL3 or YTHDF2 has been reported to stabilize IFNB1 in an m6A-dependent manner following viral infection, leading to subsequent suppression of the virus reproduction in host cell." (PMID 35120571, 2022). "On the other hand, those reader proteins identified so far in the context of these viral infections, such as YTHDF2, could be modulated positively to have antiviral activity against some herpesviruses, such as beta- and gammaherpesviruses." (PMID 36144356, 2022). "Upon activation by cytokines, tumors, and virus infection, YTHDF2 is upregulated in NK cells." (PMID 36085064, 2022).
viral infection (continued). "A recent study conducted in human foreskin fibroblasts indicated that inhibition of the m6A writer METTL3 and reader YTHDF2, led to an increase in the induction of interferon-stimulated genes after virus infection and showed that the m6A of murine Ifnb mRNA accelerated its mRNA degradtion." (PMID 31015515, 2019). "YTHDF2 pulled down VP1 and VP1 pulled down YTHDF2 as well, suggesting an interaction between YTHDF2 and VP1 in the context of viral infection." (PMID 38516932, 2024). "In this study, we have discovered that DUSP1 is a direct m6A target, and m6A and the reader protein YTHDF2 regulate DUSP1 stability to maximize the innate immune response during bacterial and viral infections." (PMID 36625590, 2023). "Knockdown of METTL3, METTL14, and YTHDF2 significantly increased viral infection and replication, while knockdown of ALKBH5 decreased viral infection and replication." (PMID 35465335, 2022). "A recent investigation conducted in human fibroblasts indicated that genes stimulated by interferon after virus infection could be induced once METTL3 and YTHDF2 were repressed, which showed that the m6A modification of murine IFNβ mRNA could accelerate its degradation." (PMID 32029706, 2020). "Meanwhile, knocking down YTHDF2, but not YTHDF1 and YTHDF3, was conducive to the viral infection and replication." (PMID 33510385, 2021).
intrahepatic cholangiocarcinoma (15 papers, 2022 to 2025). A carcinoma that arises from the intrahepatic bile duct epithelium in any site of the intrahepatic biliary tree. "Tumor-intrinsic ALKBH5 attenuates the expansion and cytotoxicity of T cells through maintaining PD-L1 expression with YTHDF2-independnet m6A modification in intrahepatic cholangiocarcinoma." (PMID 37063837, 2023). "Additionally, ALKBH5 regulated TIME by inhibiting the infiltration of MDSC-like cells and promoting PD-L1 expression on monocyte/macrophage cells via YTHDF2 in intrahepatic cholangiocarcinoma (ICC)." (PMID 39718205, 2025). "In addition, YTHDF1 and YTHDF2 facilitate the advancement of intrahepatic cholangiocarcinoma (ICC) through increasing EGFR mRNA translation and IFIT2 mRNA decay, respectively." (PMID 36999016, 2023). "Huang's team found that YTHDF2 is up‐regulated in intrahepatic cholangiocarcinoma (ICC) tissues, particularly in chemoresistant ICC, exhibiting oncogenic and cisplatin‐desensitising effects." (PMID 39135292, 2024). "In intrahepatic cholangiocarcinoma (ICC), the loss of ALKBH5 enhanced m6A abundances of PD-L1 transcripts in the 3′-UTR region in a YTHDF2-dependent manner, downregulating its expression." (PMID 36960074, 2023). "In intrahepatic cholangiocarcinoma (ICC), the m6A demethylase ALKBH5 has been shown to diminish m6A methylation on PD-L1 mRNA, shielding it from YTHDF2-mediated degradation." (PMID 40034695, 2025). "Similarly, knockdown of ALKBH5 in intrahepatic cholangiocarcinoma (ICC) cells increased m6A modifications in the 3′UTR of PD-L1 mRNA, resulting in its degradation via YTHDF2." (PMID 39987091, 2025). "In intrahepatic cholangiocarcinoma (ICC), ALKBH5 interacts with tumour PD-L1 to remove m6A deposition in the 3’UTR of PD-L1 mRNA, therefore preventing YTHDF2-mediated RNA decay and sustaining PD-L1 expression, which represses the proliferation of cytotoxic T cells." (PMID 36859310, 2023). "ALKBH5 regulated PD-L1 mRNA in a YTHDF2-dependent manner on monocytes/macrophages and infiltration of myeloid-derived suppressor-like cells in the TIME of intrahepatic cholangiocarcinoma (ICC)." (PMID 36225914, 2022). "YTHDF2 facilitates cyclin-dependent kinase inhibitor 1B (CDKN1B) mRNA degradation and plays a cisplatin-desensitizing role in intrahepatic cholangiocarcinoma (ICC)." (PMID 40483535, 2025). "Furthermore, YTHDF2 increased CDKN1B mRNA degradation in an m6A-dependent manner, which promoted intrahepatic cholangiocarcinoma (ICC) progression and reduced sensitivity to cisplatin treatment." (PMID 36517820, 2022). "Loss of ALKBH5 enhances the m6A modification on the 3’ UTR region of PD-L1 mRNA to promote its degradation in a YTHDF2-dependent manner, thus decreasing the expression of PD-L1 on monocyte/macrophage cells and increasing the infiltration of MDSC-like cells in intrahepatic cholangiocarcinoma (ICC)." (PMID 37015927, 2023).
cervical cancer (14 papers, 2020 to 2024). A primary or metastatic malignant neoplasm involving the cervix. "It was later confirmed that the reduction of YTHDF2 boosted ROS production in cervical cancer cells and increased the production of ERS-linked proteins." (PMID 38776708, 2024). "The results showed that knockdown of YTHDF2 led to an increase in the level of oxidative stress in cervical cancer cells." (PMID 38776708, 2024). "The effect of YTHDF2 knockdown on cervical cancer cell proliferation was assessed using clone formation and EdU assays." (PMID 38776708, 2024). "This study examined the correlation between YTHDF2 expression, cervical cancer stemness, and apoptosis." (PMID 38776708, 2024). "Nude mouse xenografts were generated to assess the effects of YTHDF2 knockdown on cervical cancer growth in vivo." (PMID 38776708, 2024). "Subsequently, the relationship between the expression level of YTHDF2 and the tumor stemness of cervical cancer cells was evaluated." (PMID 38776708, 2024). "This study indicates that knockdown of YTHDF2 in cervical cancer cells induces ERS through the phosphorylation of JNK." (PMID 38776708, 2024). "The protein level of GLI2 was examined by introducing SP600125 into cervical cancer cells in which YTHDF2 was knocked down." (PMID 38776708, 2024). "Sphere formation and alkaline phosphatase staining assays were performed to evaluate tumor stemness of cervical cancer cells following YTHDF2 knockdown." (PMID 38776708, 2024). "Data on apoptosis-related protein expression levels indicated that cervical cancer cells underwent apoptosis following YTHDF2 knockdown." (PMID 38776708, 2024). "•YTHDF2 knockdown suppresses the growth of cervical cancer cells and tumor stemness while also promoting apoptosis." (PMID 38776708, 2024). "Analysis of the expression data of cervical cancer in the TCGA database revealed that YTHDF2 expression was up-regulated in cervical cancer tissues compared with that in normal tissues." (PMID 38776708, 2024). "In conclusion, the knockdown of YTHDF2 significantly affects the progression of cervical cancer cells, making it a potential target for treating cervical cancer." (PMID 38776708, 2024). "The results showed that the knockdown of YTHDF2 suppressed the progression of cervical cancer cells by inhibiting tumor stemness and promoting apoptosis." (PMID 38776708, 2024). "Subsequently, analysis was conducted on the mRNA and protein expression levels of YTHDF2 in the human cervical epithelial cell line HCerEpiC and in the cervical cancer cell lines Ca Ski, C-33A, HeLa, and SiHa." (PMID 38776708, 2024). "Phosphorylation of JNK and promotion of ERS occur due to the up-regulation of GLI2 expression following the knockdown of YTHDF2 in cervical cancer cells." (PMID 38776708, 2024). "Subsequently, the differences in mRNA and protein expression of stemness-related genes, as well as YTHDF2, between the suspension-cultured cervical cancer cell lines and their parental cell lines adherently cultured in cell culture plates were compared." (PMID 38776708, 2024). "The effect of YTHDF2 knockdown on cervical cancer cell viability was evaluated using the CCK8 assay." (PMID 38776708, 2024). "Another study revealed that YTHDF2 inhibited lncRNA GAS5 in cervical cancer cells by promoting its degradation." (PMID 36816363, 2023). "In contrast, circCCDC134 gets elevated in cervical cancer as a consequence of m6A methylation, which enhances its durability through YTHDF2." (PMID 38125749, 2023). "Consistent with previous report, we found that the expression of YTHDF2 was evidently positively corrected with AKT1 expression in cervical cancer using GEPIA2 database." (PMID 36566195, 2022). "In detail, YTHDF2 knockdown restrained proliferation, promoted apoptosis, and arrested the cells at the S phase in cervical cancer cells." (PMID 33593354, 2021).
cervical cancer (continued). "Additionally, spherical cervical cancer cells in suspension culture medium promoted stemness gene expression and the up-regulation of YTHDF2." (PMID 38776708, 2024). "In the study, the effects of YTHDF2 knockdown on cervical cancer cells were investigated." (PMID 38776708, 2024). "Additionally, the size of the cervical cancer cells increased when they were suspended in spheres following YTHDF2 knockdown." (PMID 38776708, 2024). "The aim of this study was to explore whether YTHDF2 could be a therapeutic target for cervical cancer cells and to determine the possible mechanism of action to provide new therapeutic strategies for the treatment of cervical cancer." (PMID 38776708, 2024). "Taken together, high YTHDF2 expression may be necessary for maintaining tumor stemness in cervical cancer cells." (PMID 38776708, 2024). "We show how YTHDF2 controls the fate of cervical cancer cells and whether YTHDF2 could be a valid target for the therapy of cervical cancer." (PMID 38776708, 2024). "Additionally, by making circCCDC134 more stable via YTHDF2, which encourages cervical cancer (CC) spread, ALKBH5-mediated m6A methylation is in charge of its overexpression." (PMID 38125749, 2023). "YTHDF2 interference suppresses the EMT of cervical cancer cells." (PMID 36072430, 2022). "The expression of YTHDF2 was up-regulated in the cervical cancer tissues." (PMID 33593354, 2021). "For example, up-regulated YTHDF2 indicated a poor prognosis in patients with cervical cancer." (PMID 33593354, 2021). "Therefore, we investigated the effect of apoptosis in cervical cancer cells after YTHDF2 knockdown." (PMID 38776708, 2024). "For example, lncRNA GAS5-AS was reported to repress tumorigenesis and metastasis of cervical cancer by enhancing GAS5 stability and regulating m6A modifications of GAS5, which was dependent on ALKBH5 and YTHDF2." (PMID 35524319, 2022). "However, the effect of YTHDF2 on cervical cancer cell stemness has not been studied." (PMID 38776708, 2024).
Infertility (14 papers, 2017 to 2025). "Recent studies have demonstrated that the deletion of YTHDF2 resulted in the non-regulation of transcripts of related genes during oocyte maturation, leading to the infertility of specific YTHDF2 deficient female mice." (PMID 32038703, 2019). "Here we find that YTHDF2 deficiency is partially permissive in mice and results in female-specific infertility." (PMID 28867294, 2017). "Loss of the cytoplasmic reader YTHDF2 in fish impairs embryonic development as a result of defective maternal RNA clearance during maternal-zygotic transition, while in mice loss of YTHDF2 results in defective maternal RNA metabolism during oocyte maturation, leading to female-specific infertility." (PMID 30197299, 2018). "Ythdf2 deficiency causes incomplete penetrance of lethality and female-specific infertility." (PMID 29799838, 2018). "Studies have shown that METTL3-regulated m6A modification facilitates FOXO1 mRNA decay through YTHDF2 in radiation-induced lung injury and endometriosis-related infertility." (PMID 41369154, 2025). "While Ythdf2 KO females were infertile and had corpora lutea in their ovaries, indicating that ovulation has taken place but has resulted in female-specific infertility, Ythdf2 KO males were fertile and had normal seminiferous tubule histology." (PMID 38937660, 2024). "Maternal RNA degradation, which was mediated by YTHDF2, facilitated oocyte maturation; oocytes with YTHDF2 deficiency failed to change metaphase II (MII) transcriptome, leading to female-specific infertility in mice." (PMID 35859892, 2022). "Recently, another study has shown that the number of related gene transcripts cannot be changed during the development in oocytes of YTHDF2-messing mice; this phenomenon leads to infertility in this mouse." (PMID 35958303, 2022). "In summary, YTHDF2 deletion is partially permissive in mice and results in female-specific infertility." (PMID 28867294, 2017). "Therefore, YTHDF2 knockout leads to female-specific infertility." (PMID 34568313, 2021). "In summary, we revealed that METTL3-mediated m6A disrupts the cellular decidual process by promoting the YTHDF2-dependent decay of FOXO1 mRNA, thereby contributing to defective endometrial receptivity in infertile women with endometriosis." (PMID 37891533, 2023). "The findings of the present study indicate that METTL3-mediated m6A modification impairs the decidualization of endometrial stromal cells by promoting YTHDF2-dependent degradation of FOXO1 mRNA, thus affecting embryo implantation and resulting in endometriosis-related infertility to a large extent." (PMID 37891533, 2023).
osteosarcoma (13 papers, 2020 to 2025). A usually aggressive malignant bone-forming mesenchymal neoplasm, predominantly affecting adolescents and young adults. "- circ_0001105 can inhibit the development of osteosarcoma by sponging miR-766.- Overexpressed miR-766 promotes colony formation ability and viability of osteosarcoma cells by targeting YTHDF2." (PMID 37205191, 2023). "Recently, studies constantly pay attention to the role of YTHDF2 in the progression of osteosarcoma." (PMID 33593354, 2021). "And down-regulated YTHDF2 predicted more aggressive tumor phenotypes and a worse prognosis of osteosarcoma." (PMID 33593354, 2021). "The regulatory effect of YTHDF2 on stem cells on cancer has been confirmed in many cancers, such as acute leukemia and osteosarcoma." (PMID 33195193, 2020). "We next shed light on the expression of YTHDF2 in osteosarcoma and the role of YTHDF2 on HMBOX1 expression in osteosarcoma." (PMID 32814762, 2020). "Importantly, to validate the biological function of m6A regulators in sarcoma, we performed loss of function experiments for two regulators, YTHDF2 and HNRNPA2B1 in osteosarcoma cell line." (PMID 35847857, 2022). "Also, the findings offered evidence that YTHDF2 took a part in the tumorigenesis and progression of osteosarcoma through adjusting the circ_0001105/miR-766 axis." (PMID 33593354, 2021). "YTHDF2 was found to cooperate with a circRNA in the development of osteosarcoma." (PMID 33593354, 2021). "Firstly, YTHDF2 was discovered to be down-regulated in osteosarcoma tissues." (PMID 33593354, 2021). "Nevertheless, current research on m6A methylation modifications in osteosarcoma has predominantly focused on METTL3, METTL14, WTAP, ALKBH5, and YTHDF2, with few studies on other m6A methylation regulators." (PMID 40176793, 2025). "YTHDF2 can directly bind to the 3’-UTR of TRIM7 mRNA and negatively regulate the expression of TRIM7 in osteosarcoma HOS and MG63 cells." (PMID 34094986, 2021).